GRB7 (growth factor receptor bound protein 7)
Diseases named in the same sentence as GRB7 in open-access papers (continued):
Sharing a sentence is not in itself a finding about the gene and the disease.
cancer (continued). "In conclusion, this Grb7 inhibitory peptide has potential to be developed as a therapeutic agent alone, in combination with traditional chemotherapy, or in combination with other targeting molecules for the treatment of cancer." (PMID 17426702, 2007). "Combining chemotherapy with molecules, such as our Grb7 peptide, may have great potential at effectively killing the cancer cells and minimising toxicity." (PMID 17426702, 2007). "This Grb7 inhibitory peptide has potential to be developed as a therapeutic agent alone, in combination with traditional chemotherapy, or in combination with other targeting molecules for treatment of cancer." (PMID 17894853, 2007). "Downregulating Grb7 either by anti-sense or siRNA technology has shown to inhibit the invasive or proliferative properties of cancer cells." (PMID 17426702, 2007). "Importantly, our findings revealed that GRB7 is preferentially expressed in malignant cells compared to immune cells across a variety of cancer types, suggesting that GRB7 may be a promising target for future therapeutics." (PMID 39204147, 2024). "Therefore, an alternative may be to use GRB7 as a therapeutic target, as inhibiting GRB7 may weaken cancer cell growth and lead to cell death by blocking multiple oncogenic signalling pathways." (PMID 32737994, 2020). "Additionally, several upstream signals contribute to Grb7-mediated cancer migration." (PMID 31083325, 2019). "Moreover, tyrosine phosphorylation of Grb7 has also been shown to regulate cancer migration." (PMID 31083325, 2019). "Notably, targeted knockdown of genes in the ERBB2 amplicon, including GRB7, leads to an additive effect on the decreased cell-cycle progression and cancer proliferation, emphasizing the importance of GRB7 coamplified with ERBB2 in their contribution to cancer proliferation." (PMID 31083325, 2019). "Additionally, the human GRB7 gene is located on chromosome 17q12, in close proximity to the cancer-associated ERBB2 gene, which has been identified as an ERBB2 amplicon, suggesting the coamplification and coexpression of Grb7 and ERBB2 contribute to cancer development." (PMID 31083325, 2019). "Analyses of Cancer Cell Line Encyclopedia (CCLE) datasets showed that both mRNA and protein levels of GRB7 were higher in OC than in most other cancers." (PMID 39204147, 2024). "An inhibitory peptide (G7-18NATE) has been developed which binds specifically to the GRB7 SH2 domain and is able to attenuate cancer cell proliferation and migration in various cancer cell lines." (PMID 36686796, 2022). "The cancer genes are composed of genes that code for HER2 (HER2 and GRB7), oestrogen genes (ER, PGR, BCL2, and SCUBE2), proliferation genes (MKI67, STK15, BIRC5, CCNB1, and MYBL2), and invasion genes (MMP11 and CTSL2) as well as GSTM1, CD68, and BAG1." (PMID 36042999, 2022). "Affected genes included FGFR1, IRS1, CLDN4, GRB7, and VCAN, while EZR and MYC were commonly affected in at least four out of five progression stages of the selected cancer levels." (PMID 34069906, 2021). "As such, GRB7 likely transmits signalling through PI3K/mTOR, MAPK, and RTKs, but also has a role in apoptosis, enabling cancer cells to proliferate and survive." (PMID 32737994, 2020). "According to the structure-based progression, a new optimized bicyclic peptide that displays high specificity for the SH2 domain of Grb7 has been recently developed to block the interaction between Grb7 and the ERBB family in cancer cells." (PMID 31083325, 2019). "In these cancer cells, mitogen-activated protein kinases (MAPKs), such as JNK or ERK, are crucial downstream signals regulated by Grb7 in promoting cancer movement." (PMID 31083325, 2019). "Through interactions with the ERBB protein family, Grb7 has been found to transmit and amplify the oncogenic ERBB protein family-mediated signal transduction cascades that play key roles in regulating cancer development." (PMID 31083325, 2019).
cancer (continued). "The copy number and expression levels of both GRB7 and ERBB2 are highly increased in many human cancers." (PMID 31083325, 2019). "The following will describe and discuss in detail the development of a Grb7 expression-based prognostic assay and Grb7-related therapeutics in ERBB family-mediated cancers." (PMID 31083325, 2019). "Grb7 is an adapter protein, overexpressed in HER2+ve breast and other cancers, and identified as a therapeutic target." (PMID 31627265, 2019). "A number of cancer-related genes are located in these two RARs: NUPR1, MVP, MAPK3, FUS, and PYCARD are located in RAR-G12 while ERBB2, GRB7, and PPP1R1B are located in RAR-G13." (PMID 22938721, 2012). "We propose that the current study will assist with the development of second generation Grb7 SH2 domain inhibitors, potentially leading to novel inhibitors of cancer cell migration and invasion." (PMID 17894853, 2007). "Recently, an inhibitory peptide (G7-18NATE) has been developed which binds specifically to the Grb7 SH2 domain and is able to attenuate cancer cell proliferation and migration in various cancer cell lines." (PMID 17894853, 2007). "Another study developed a multi-epitope vaccine targeting important cancer antigens like STAT3, HER2, and GRB7 using a multimodal strategy that included MHC I, MHC II, CTL, and B-cell epitopes created from MAGE-A3, EGF, and MUC-1 by in silico immunoinformatics techniques." (PMID 40453095, 2025). "Additionally, EGF-induced GRB7 tyrosine phosphorylation activates Ras-GTPases and extracellular signal-regulated kinases 1/2 (ERK1/2) contributes to cancer proliferation." (PMID 39204147, 2024). "Validating these antibodies is also important since GRB7 and PGAP3 may themselves serve as important genes for tumor biology in breast and other cancers." (PMID 37809181, 2023). "Taken together, our study provides strong evidence for an oncogenic role for GRB7 in OAC and suggests that targeting GRB7 may be a potential therapeutic strategy for this cancer." (PMID 32737994, 2020). "Additionally, the Grb7 peptide that ablates the interaction between Grb7 and protein tyrosine kinases, including the ERBB family, significantly attenuates cancer movement." (PMID 31083325, 2019). "Furthermore, a summary of the potential clinical applications of Grb7 as a prognostic marker and a therapeutic target in ERBB family-driven cancers is also provided." (PMID 31083325, 2019). "In addition, specific Grb7 peptides targeting the SH2 domain of Grb7, which blocks EGF/EGFR signal-mediated ERK activation, or knockdown of GRB7, which ablates MMP-9 expression, attenuate cancer invasion." (PMID 31083325, 2019). "Furthermore, combination treatment with the Grb7 peptide and ERBB family-targeted drugs display cooperative functions in cancer therapy." (PMID 31083325, 2019). "However, the functional role and pathological significance of Grb7 in vivo, during the entire process of ERBB family-mediated cancer development, as well as tumor microenvironment formation need to be illustrated." (PMID 31083325, 2019). "In addition, EGF-triggered Grb7 tyrosine phosphorylation activates Ras-GTPases and promotes the phosphorylation of ERK1/2, which, in turn, stimulates cancer proliferation and growth." (PMID 31083325, 2019). "Moreover, several studies have revealed that the consistent upregulation of Grb7 and the ERBB family facilitates the development of cancer malignancies." (PMID 31083325, 2019). "Although linage specific analysis in RNAi data excluded genes that are important drivers for multiple cancers as well as ESCC, such as ERBB2 and EGFR, through knockdown assays in ESCC cell lines and additional survival analysis, we confirmed GRB7 as a new driver gene in ESCC." (PMID 26465158, 2015). "Interestingly, Grb7 is located on the HER2 amplicon, is co-amplified and co-overexpressed with HER2 in cancer, and physically interacts with HER2, HER3, and HER4." (PMID 20126311, 2010).
cancer (continued). "Although the precise downstream activities of Grb7 are not yet known, there is compelling evidence that Grb7 represents an important new cancer target." (PMID 17894853, 2007). "However, a comprehensive bioinformatics analysis of GRB7's role across pan-cancer tissues using multiple databases has not yet been conducted." (PMID 39742197, 2024). "Finally, growth factor receptor bound 7 (GRB7), a multidomain adaptor protein that was previously shown to interact with the H. pylori CagA effector protein, is a critical mediator of EGFR/ErbB signaling involved in cancer development." (PMID 37193047, 2022). "We had previously shown that G7-peptides were able to disrupt Grb7 interactions with upstream binding partners, but it was not yet known whether the second generation peptides possess improved anti-cancer activity over G7-18NATE-Pen." (PMID 31627265, 2019). "In univariate analysis, we found 17 significant genes, located on 3p14.1, 3q13.2, 17q12, and 18q22.1; these genes included cancer-related genes, such as FOXP1, GRB7, and NFATC1, indicating that altered expression of specific genes through CNAs could influence the clinical course of patients." (PMID 26465158, 2015). "Since GRB7 is a molecular adaptor for EGFR receptor tyrosine kinases, including ERBB2, the amplification of GRB7 may have a functional consequence in Her-2 driven cancers." (PMID 24874471, 2014). "Additionally, the specific Grb7 peptide targeting the SH2 domain of Grb7 efficiently reduces the formation of the Grb7 and ERBB family complex and leads to the attenuation of 3D culture colony formation, which reflects a combination of anti-proliferative and/or pro-apoptotic effects on cancer cells." (PMID 31083325, 2019). "Intrinsically, our studies indicated that EGF-induced de novo Grb7 tyrosine phosphorylation/activation is essential for the tumorigenicity, suggesting that expression and activation of both Grb7 and EGFR might collaboratively function as a critical point in cancer developmental processes." (PMID 31083325, 2019). "In addition, studies have shown that PGAP3, GRB7, STARD3, and PSMD3 are significantly positively correlated with STAT3 in TCGA cancers; however, reports on these are lacking." (PMID 36977736, 2023).
tumor (57 papers, 2002 to 2025). "GRB7 is an oncogene, participating in various signaling pathways implicated in cell migration, metastatic invasion, cell proliferation and tumor-associated angiogenesis." (PMID 36434634, 2022). "Intriguingly, we found among the 6 digestive systems tumor types, GRB7 was most significantly associated with prognosis in PDAC, further emphasized the clinical importance of GRB7 in PDAC." (PMID 36434634, 2022). "Moreover, GRB7 gene expression was observed to be associated with immune infiltration, highlighting its potential effect on the tumor microenvironment." (PMID 39742197, 2024). "The TIMER database was used to explore the connection between GRB7 expression in tumor tissues and the infiltration of immune cells." (PMID 39742197, 2024). "Our results showed that the ablation of GRB7 in the OVCAR3 cell line significantly enhanced the vulnerability of these tumor cells to the cytotoxic effects of CD8+ T cells." (PMID 39204147, 2024). "The association of GRB7 and HER2 with Type 2 T-helper cells, and the role of local Th2 inflammation in fostering an immunosuppressive environment that promotes tumor progression, has been noted." (PMID 39204147, 2024). "Silencing of GRB7 significantly induced slower growth of tumors and reduced the tumor volumes compared to those in the shCtrl group." (PMID 38129809, 2023). "Low PPP1R1B mRNA expression was also linked to worse prognosis of patients with ER positive tumours, and CDC42 and GRB7, amongst others, were identified as PPP1R1B related genes using Artificial Neural Network (ANN) analysis." (PMID 38036593, 2023). "Our in vivo results supported the idea that depletion of GRB7 suppressed tumor growth and downregulated Ki67 expression in gastric cancer tumor tissue of mice." (PMID 38129809, 2023). "Further, GRB7 promotes tumor proliferation, migration, invasion, and metastasis in several tumor types by interacting with the ERBB protein family." (PMID 35790975, 2022). "In detail, GRB7 was positively correlated with tumor growth size (T classification), lymph node metastasis (N classification), and distant organ and tissue metastasis (M classification)." (PMID 36686796, 2022). "Tumours collected from mice at diestrus exhibited a significant increase in the expression of genes Mki67 (p = 0.05), Ccnb1 (p = 0.02), Erbb2 (p = 0.03), Grb7 (p = 0.02), and Bag1 (p = 0.05), compared to tumours collected at estrus." (PMID 34174867, 2021). "Growth factor receptor bound protein 7 (GRB7) is an important adaptor protein that is primarily involved in regulating tumor invasion and metastasis, as well as mammalian embryo migration." (PMID 34783299, 2021). "GSEA was used to assess the contribution of GRB7 to the malignant progression phenotype of the tumor." (PMID 33162827, 2020). "Consistent with this, GRB7 knockdown in vivo with an inducible shRNA significantly inhibited tumour growth in cell line xenografts." (PMID 32737994, 2020). "The role of GRB7 in tumor proliferation and tumorigenesis was explored by establishing stable cells, in vitro cell experiments and in vivo xenograft models." (PMID 33162827, 2020). "In support of this idea, we show that GRB7 orchestrates OAC tumour cell growth, survival, and migration in cell line models." (PMID 32737994, 2020). "Noticeably, GRB7 knockdown alone initially prevented tumour growth but tumour volume began to increase around 17 days after commencing treatment with doxycycline." (PMID 32737994, 2020). "In order to pursue GRB7 as a therapeutic target, we further functionally characterised long‐term GRB7 knockdown and its anti‐tumour activity in vivo." (PMID 32737994, 2020). "We next investigated the anti‐tumour activity of GRB7 inhibition and/or trastuzumab in vivo over the time course of the treatment." (PMID 32737994, 2020). "An important finding here is that tumour growth suppression is achieved through depletion of GRB7 in HER2‐ and GRB7‐overexpressed, but trastuzumab‐insensitive, tumour cells." (PMID 32737994, 2020).
tumor (continued). "In OE19 xenografts, tumour growth was completely inhibited by trastuzumab alone or in combination with GRB7 knockdown." (PMID 32737994, 2020). "Consistent with this, GRB7 protein expression in tumours showed a gradual increase over time despite continued treatment with doxycycline in a separate cohort of six mice." (PMID 32737994, 2020). "miR-193a-3p has been shown to directly target the 3′ UTR of GRB7, suggesting possible Grb7-targeted therapies by tumor suppressor miRNAs." (PMID 31083325, 2019). "As examples of positive controls, the proteomic analysis unambiguously detected the high amplification and overexpression of the Her2 and Grb7 proteins, which are the known markers of Her2 tumours." (PMID 26725330, 2016). "As expected, the two Her2 markers, namely, Her2 and Grb7, which are known to be co-amplified in Her2 tumours were significantly different on all three levels." (PMID 26725330, 2016). "This series of analyses suggest that GRB7, located on 17q12, was overexpressed due to copy number gains and play a critical role in tumor growth and invasion." (PMID 26465158, 2015). "Consistent with the results of integrative analysis, GRB7 was significantly upregulated in tumor tissues compared to the corresponding normal mucosa." (PMID 26465158, 2015). "First, to validate GRB7 overexpression in ESCC tumor tissue, we compared GRB7 mRNA expression levels in tumor tissues with corresponding normal mucosa." (PMID 26465158, 2015). "The mRNA and protein expression pattern in this tumor is nonetheless consistent with the concept of GRB7 gene being the focus of 17q11-12 amplification and selective retention." (PMID 24102037, 2013). "The GRB7 gene codes for a multi-domain signal transduction molecule, and is known to play important roles in tumor growth and migration (Shen & Guan [2004])." (PMID 24102037, 2013). "As expected, GRB7 stably expressing A2780cp cells exhibited 30% faster tumor growth as compared with the vector control (P = 0.020, Student t-test)." (PMID 23285101, 2012). "There were two genes, in addition to HER2, clearly overexpressed in HER2+ tumours, GRB7 and MED24, which are both upstream of ERBB2 on chromosome 17 and previously associated with the HER2+ subtype." (PMID 22067903, 2011). "Tumours co-expressing high levels of Grb7 and HER2 have a worse outcome than those with only higher levels of HER2, in line with the clinical data presented here." (PMID 20628393, 2010). "Grb7 is an SH2 containing adapter protein, which is known to associate with several tumour-related molecules." (PMID 17426702, 2007). "Co-expression of Grb7 with ErbB2 was detected in 31% of esophageal carcinomas and was significantly correlated with extramucosal tumour invasion." (PMID 17426702, 2007). "However, the scope of these findings of OC, derived from a limited number of cell lines and small tumor tissue samples, calls for a more comprehensive analysis of GRB7’s expression and its impact on OC." (PMID 39204147, 2024). "GRB7 has been identified as a vital regulator in tumor progression." (PMID 38129809, 2023). "Additionally, we found that the expression level of GRB7 protein was positively correlated with the self-renewal potential representing tumor cell metastasis, chemotherapy resistance, and recurrence." (PMID 36686796, 2022). "Studies that have assessed its expression in tumor samples, suggest the role of GRB7 as an adaptor protein that binds to tyrosine kinase receptors like HER2, to amplify its signal and mediate the activation of several downstream proteins involved in cell migration and survival pathways." (PMID 36620598, 2022). "Confirming the CNV-by-exome analysis, ddPCR analysis of Grb7 and Mien1, which are located close to Erbb2 in both mouse and human (the locus is syntenic in the two species), demonstrated similar levels of amplification in the tumours to Erbb2/Neu." (PMID 34003256, 2021).